FSCN1 (fascin actin-bundling protein 1)
Diseases named in the same sentence as FSCN1 in open-access papers (continued):
Sharing a sentence is not in itself a finding about the gene and the disease.
adenoma (1 paper, 2022). A neoplasm arising from the epithelium. "Specifically, FSCN1 is widely expressed in 16% of adenomas and between 17% and 26% of adenocarcinomas." (PMID 35711849, 2022). "In adenomas, FSCN1 and Ki67 expressions are often inversely correlated at the cellular level, but this trend is less evident in adenocarcinomas." (PMID 35711849, 2022). "However, FSCN1 is expressed in subsets of adenomas and colorectal adenocarcinomas." (PMID 35711849, 2022).
Bowen’s disease (1 paper, 2022). "Our proteomics results showed expression of FSCN1 and ACTN1 were significant higher in CSCC relative to Bowen disease, and FSCN1 as well as ACTN1 may related to the proliferation, invasion and migration in CSCC progression process." (PMID 36085041, 2022). "And next, among 20 proteins, 8 proteins (TNC, FSCN1, SERPINB1, ACTN1, RAB31, COL3A1, COL1A1 and CD36) expressed levels showed significant differences between CSCC and Bowen disease." (PMID 36085041, 2022). "Furthermore, the relative expression levels of TNC, FSCN1, SERPINB1 in the Bowen disease were also significantly increased, while the COL3A1 were also significantly decreased relative to the healthy control." (PMID 36085041, 2022). "Besides, the proteins of TNC, FSCN1, SERPINB1, ACTN1 and RAB31 in CSCC were significantly up-regulated, while COL3A1, COL1A1 and CD36 were significantly down-regulated relative to Bowen disease in proteomics results." (PMID 36085041, 2022).
Burkitt lymphoma (1 paper, 2021). A rare form of malignant mature B-cell non-Hodgkin lymphoma. "While FSCN1-negative Hodgkin’s lymphoma-derived cell lines also show upregulated FSCN1 levels, LMP1-negative Burkitt lymphoma-derived cell lines are negative for FSCN1 expression." (PMID 34830909, 2021).
Castleman disease (1 paper, 2021). Castleman disease (CD) is a benign lymphoproliferative disorder that may present as a localized or multicentric form. "While lymphocytes, myeloid, and plasma cells stain negative for FSCN1, in human hematologic malignancies including HIV-related lymphoid hyperplasia, Reed-Sternberg cells, Hodgkin’s lymphoma, Castleman’s disease, and other lymphoid hyperplasia, FSCN1 is overexpressed." (PMID 34830909, 2021).
cholangiomas (1 paper, 2021). "The AKT/FSCN1 lesions display enhanced proliferation as gauged by EdU incorporation, they exhibited cholangiocellular features based on the immunoreactivity for the CK19 and A6 markers, and histopathologic analyses indicated them as neoductular proliferation or cholangiomas." (PMID 34155338, 2021).
choroidal neovascularization (1 paper, 2023). An eye disorder described by the growth of new blood vessels that originate from the choroid through a break in the Bruch membrane into the sub–retinal pigment epithelium (sub-RPE) or subretinal space. "We also used a laser-induced choroidal neovascularization (CNV) model to determine the role of FSCN1 in pathological choroidal neovascularization in vivo." (PMID 37596693, 2023). "We discovered that Fascin homologue 1 (FSCN1) is vital for angiogenesis both in vitro and in vivo, and that it is highly expressed in oxygen-induced retinopathy (OIR) and laser-induced choroidal neovascularization (CNV)." (PMID 37596693, 2023). "Bioinformatics analysis and quantitative RT-PCR were used to detect and verify the FSCN1 expression levels in oxygen-induced retinopathy (OIR) and laser-induced choroidal neovascularization (CNV) mice model." (PMID 37596693, 2023).
colorectal tumors (1 paper, 2022). "In 47% of colorectal tumors, FSCN1 expression is increased in the surrounding stroma regardless of the level of FSCN1 in the tumor." (PMID 35711849, 2022).
cortical dysplasia (1 paper, 2017). "FSCN1-related pathways mainly participate in the migration of neurons, which was known as a key mechanism of cortical dysplasia." (PMID 28222113, 2017). "And FSCN1, CRMP1, NDRG1, DPYSL5, MAP4, and FABP3 were selected for validation and identified to be increased in childhood cortical dysplasia patients, while PRDX6 and PSAP were identified decreased." (PMID 28222113, 2017).
Down syndrome (1 paper, 2013). "Fascin-1 (Fscn1), an actin cross-linking protein abundant in most brain cell types, is thought to anchor key components in the synaptic region and is upregulated in an animal model of Down syndrome." (PMID 23738220, 2013).
endometrial carcinoma (1 paper, 2021). A malignant tumor arising from the epithelium that lines the cavity of the uterine body. "In undifferentiated endometrial carcinomas, the studies reported a loss of E-cadherin and β-catenin and overexpression of FSCN1, galactin-3, cyclin D1, and p16, which is involved in EMT and invasion, thus contributing to aggressive behavior and poor prognosis." (PMID 34830909, 2021). "Another investigation revealed significant overexpression of FSCN1 in proliferative endometrial carcinoma samples as compared with the control samples with a significant association with tumor grade and neural invasion." (PMID 34830909, 2021).
endometrioid adenocarcinoma (1 paper, 2021). An adenocarcinoma characterized by the presence of malignant glandular epithelial cells resembling endometrial cells. "Moreover, high FSCN1 scoring was associated with poorer tumor differentiation in serous, mucinous, and endometrioid adenocarcinoma, indicating a role of FSCN1 in analyzing tumor aggressiveness, and was suggested as an independent prognostic risk factor in mucinous carcinoma." (PMID 34830909, 2021).
endometriosis (1 paper, 2025). The growth of functional endometrial tissue in anatomic sites outside the uterine body. "Targeting FSCN1 or its regulatory pathways, such as miR-145 modulation, offers a promising avenue for therapeutic intervention in endometriosis." (PMID 40072086, 2025). "Emerging evidence highlights FSCN1’s role in endometriosis, particularly in driving the invasive behavior of ectopic endometrial cells." (PMID 40072086, 2025).
epilepsy (1 paper, 2017). A brain disorder characterized by episodes of abnormally increased neuronal discharge resulting in transient episodes of sensory or motor neurological dysfunction, or psychic dysfunction. "So it is possible that, in our study, the increased level of FSCN1 indicates an abnormally enhanced neurogenesis, neurite outgrowth and neuronal migration, and thus, result in CCD and epilepsy." (PMID 28222113, 2017).
gynecological cancer (1 paper, 2021). "Here we discuss the current knowledge of FSCN1 and its underlying mechanisms in order to elucidate its multiple roles in the onset and progression of gynecological cancer." (PMID 34830909, 2021). "Thus, evaluating FSCN1 expression as a biomarker depicting the progression and outcomes of several types of gynecological cancers has been the center of renewed interest." (PMID 34830909, 2021).
hepatocellular adenoma (1 paper, 2021). A benign epithelial neoplasm arising from the hepatocytes. "Furthermore, we detected the presence of hepatocellular adenomas or hepatocellular foci, or of mixed lesions, in AKT/FSCN1 and AKT/TAZ livers." (PMID 34155338, 2021).
Hypoglycemia (1 paper, 2025). A decreased concentration of glucose in the blood. "In this study, we report that systemic knockout (KO) of Fscn1 leads to 52.2% mortality within 24 h post-birth, accompanied by severe hypoglycemia in KO pups compared with their littermates." (PMID 40884159, 2025).
hypopharyngeal cancer (1 paper, 2021). Carcinoma, predominantly squamous cell, arising from the epithelial cells of the hypopharynx. "It is required for hypoxia-induced overexpression of FSCN1 in pancreatic and hypopharyngeal cancer cells." (PMID 33614909, 2021).
intracranial meningioma (1 paper, 2021). A meningioma that arises within the cranial cavity. "Similarly, for patients with spinal or intracranial meningioma, it has been demonstrated that no relation exists between the tissue expression of FSCN1 and age (<60 vs ≥60 years; p = 0.693)." (PMID 34737886, 2021).
leiomyosarcoma (1 paper, 2013). An uncommon, aggressive malignant smooth muscle neoplasm, usually occurring in post-menopausal women.
liver cirrhosis (1 paper, 2024). "The results of this study showed that the positivity rate of FSCN1 in HCC was 13.9%, while the positivity rate in normal liver tissue and liver cirrhosis tissue was 0%, suggesting that FSCN1 plays an important role in the occurrence and development of HCC." (PMID 38698008, 2024). "The immunehistochemical analysis was used to detect the expression of FSCN1 in 108 cases of HCC, 26 cases of ICC, 23 cases of liver cirrhosis, and 11 cases of normal liver tissues." (PMID 38698008, 2024). "Notably, the positivity rates and strong positivity rates of FSCN1 in ICC tissues were significantly higher than those in HCC, liver cirrhosis, and normal liver tissues (P < 0.01 for all comparisons)." (PMID 38698008, 2024).
male infertility (1 paper, 2025). The inability of the male to effect fertilization of an ovum after a specified period of unprotected intercourse. "Notably, several SNPs associated with parental interaction effects in the ART sample mapped to genes previously implicated in male infertility, including ACTB, FSCN1, and RNF216." (PMID 41325449, 2025).
metastatic carcinoma (1 paper, 2017). A carcinoma which has spread from the original site of growth to another anatomic site. "Reports concerning FSCN1 as a novel therapeutic biomarker for aggressive and metastatic carcinomas are limited." (PMID 29142206, 2017).
monoclonal gammopathy of undetermined significance (1 paper, 2021). "We found that FSCN1 was dramatically down-regulated in MM compared to normal donors (p < 0.001) and monoclonal gammopathy of undetermined significance (MGUS) (p = 0.032)." (PMID 33753991, 2021).
mucinous carcinomas (1 paper, 2021). "Moreover, FSCN1 overexpression was associated with advanced cancer stage, poorer histological differentiation, and survival rate of mucinous carcinoma, suggesting a potential role of FSCN1 as a candidate biomarker for aggressive serous and mucinous carcinomas." (PMID 34830909, 2021).
myeloma (1 paper, 2021). "To explore the relationship between FSCN1-3 expression levels and the progression of myeloma, we also analyzed FSCN1-3 expression levels of patients from GSE2113 in three different myeloma stages, including MGUS, MM and PCL." (PMID 33753991, 2021).
non-small cell lung adenocarcinoma (1 paper, 2022). Type of epithelial lung cancer arising from glandular origin. "Inhibition of FSCN1 decreases the activity of MAPK pathway, and targeting FSCN1 may inhibit the growth and metastasis of non-small-cell lung adenocarcinoma cells." (PMID 35602576, 2022).
primary immunodeficiency (1 paper, 2024). "Single-gene enrichment analysis showed that IFI6 and FSCN1 were enriched in the intestinal immune network of the immunoglobulin A production pathway in SSc, whereas IFI6 and FSCN1 were enriched in the primary immunodeficiency signaling pathway in patients with AS." (PMID 39050259, 2024).
renal fibrosis (1 paper, 2025). A final common manifestation of a wide variety of chronic kidney diseases characterized by glomerulosclerosis and tubulointerstitial fibrosis. "Among the genes predicted to be regulated by p300 in proximal tubule cells during renal fibrosis, we selected the POSTN, FSTL1, and FSCN1 genes, as these encode secreted proteins that mediate interactions with surrounding cells and affect the mesenchymal transition." (PMID 40588562, 2025). "ATAC-sequencing analysis of PTCs from an ischemia-reperfusion injury-induced renal fibrosis mouse model (GSE197815) revealed increased chromatin accessibility in the promoter regions of POSTN, FSTL1, and FSCN1 genes during the progression of renal fibrosis." (PMID 40588562, 2025). "Interestingly, increased p300 in proximal tubular cells (PTCs) promoted renal fibrosis development by mediating the endothelial to mesenchymal transition (EndMT) via upregulation of the mesenchymal-transition-related secreted proteins POSTN, FSTL1, and FSCN1." (PMID 40588562, 2025). "Based on our demonstration that p300 promotes the secretion of POSTN, FSTL1, and FSCN1 in renal proximal tubule cells, thereby increasing the EndMT, we next investigated whether selective inhibition of p300 suppressed the secretion of these three proteins in a UUO-induced renal fibrosis mouse model." (PMID 40588562, 2025).
uterine carcinosarcoma (1 paper, 2021). A usually aggressive malignant neoplasm arising from the uterine corpus and less often the cervix. "Uterine carcinosarcoma cases were assessed for FSCN1 expression using IHC; while FSCN1 was absent in benign cases, it was present in both malignant epithelial and mesenchymal elements of uterine carcinosarcomas." (PMID 34830909, 2021).
viral infection (1 paper, 2019). "Some proximal genes targeted by these 6 REs (FSCN1, GSTP1, JAM3, CHRNA6, NFAT5, and PRRC2A) are related to immune response, viral infection, and/or HCC based on ontological analysis." (PMID 31639042, 2019).
tumor (114 papers, 2010 to 2026). "FSCN1 protein presence was investigated in different tumour types, and it was correlated with increased risk of disease progression, metastasis, and mortality." (PMID 41226387, 2025). "Differences in the levels of FSCN1+ tumor cells, FSCN1+ tumor-associated macrophages, and fibroblasts in tumor tissues were observed with respect to lymph node metastases and tumor progression." (PMID 40669873, 2025). "The UALCAN database also showed that higher FSCN1 expression in HCC patients with the same tumor grade was associated with a shorter survival period." (PMID 40093808, 2025). "FSCN1 has been previously implicated in tumor cell growth and metastasis, further highlighting its potential role in regulating cell migration." (PMID 38218854, 2024). "Regarding the clinical characteristics, only the FSCN1 rs1640233 polymorphism of the CC genotype was significantly associated with developing tumor size and lymph node involvement among BC cases (p-value = 0.04 and 0.02, respectively)." (PMID 38587571, 2024). "Consistent with the in vitro observations, FASN knockdown markedly inhibited tumor growth in mice, which was associated with FSCN1." (PMID 39075049, 2024). "Previous studies have reported that FSCN1, which is localized in filopodia underneath the plasma membrane, is associated with increased cell motility, cell invasion, and aggressive tumor behavior." (PMID 37596693, 2023). "The overexpression of fascin actin-binding protein 1 (FSCN1) has been associated with tumor malignant phenotypes." (PMID 38077434, 2023). "In this regard, it is noteworthy that within the TME, besides DCs tumor-associated macrophages (TAMs) also expressed Fscn1 at a high level." (PMID 35681718, 2022). "The overexpression of FSCN1 in NSCLC has been previously reported to be associated with tumor growth, migration, invasion, and metastasis." (PMID 35681609, 2022). "We started with investigations on the F‐acting bundling protein Fascin1 (FSCN1), a key regulator of cytoskeleton dynamics, previously associated with tumor growth, migration, invasion, and metastasis." (PMID 35156321, 2022). "TMA analysis showed higher FSCN1 expression in the tumor stroma than in cancer compartments, and this was associated with the advanced tumor stage." (PMID 34830909, 2021). "The authors found that FSCN1 expression was associated with the increased risk of intraperitoneal tumor growth and spread." (PMID 34830909, 2021). "The overexpression of FSCN1 in cancer cells has been associated with tumor growth, migration, invasion, and metastasis." (PMID 33614909, 2021). "In fact, in our screening pipeline, we only considered the candidate genes which was up-regulated in tumor tissues and identified one gene (FSCN1) that was associated with prognosis and response to radiotherapy in PIK3CA-altered patients." (PMID 34249689, 2021). "Increased FSCN1 expression is associated with poor clinicopathological outcomes including advanced tumor stage, grade, and lymph node invasion with poor overall survival and disease-free survival rates." (PMID 34830909, 2021). "To investigate the predictive power of circulating levels of FSCN1 in the tumor progression, we evaluated any association between pre-surgery FSCN1 concentrations and clinical characteristics of ACC patients." (PMID 34248854, 2021). "Due to heterogeneity in different cancer cells and the complexity of multiple molecular mechanisms underlying tumor progression, evidence regarding FSCN1 roles in cancer development and progression is fragmented and limited." (PMID 33614909, 2021). "Meanwhile, FSCN1 expression levels were significantly associated with tumor size, TNM stage and distant metastasis (p < 0.05)." (PMID 32042551, 2020). "The overexpression of FSCN1 is commonly associated with distant metastasis, tumor progression, malignant infiltration and poor prognoses." (PMID 32699531, 2020).